PNPLA3 (patatin like domain 3, 1-acylglycerol-3-phosphate O-acyltransferase )
Diseases named in the same sentence as PNPLA3 in open-access papers (continued):
Sharing a sentence is not in itself a finding about the gene and the disease.
liver disease (continued). "For this reason, individuals with PMS who have lost a copy of PNPLA3 and/or PPARA should be screened for variants in the remaining copy and eventually follow a low-calorie, alcohol-free dietary regimen to reduce the risk for liver disease." (PMID 35328081, 2022). "Metabolic alterations, mostly type 2 diabetes (T2DM) and obesity, as well as genetic predisposition, especially polymorphism in the patatin-like phospholipase domain-containing protein 3 (PNPLA3) gene, are risk factors for NAFLD onset and progression towards advanced liver disease." (PMID 35276911, 2022). "HSD17B13 and PNPLA3 have both been shown to localize to lipid droplets, but it is not yet understood to what extent the alteration in TG composition is a primary contributor to the severity of liver disease." (PMID 35411667, 2022). "The effect of the PNPLA3 G/G genotype on the risk of developing severe liver disease was more pronounced for patients without advanced fibrosis at baseline." (PMID 36166317, 2022). "As a result, PNPLA3 is considered as a central player in the development of liver disease." (PMID 34711009, 2021). "In this study by Dunn and co-workers, patients carrying the PNPLA3 rs738409 G-allele did not have more severe liver disease at BL but showed less pronounced decreases in CTP score after HCV cure." (PMID 33917196, 2021). "This is in line with other reports, according to which carriage of the PNPLA3 mutation is a risk factor for liver disease progression and HCC in Caucasians but not in Asians." (PMID 32382265, 2020). "The genetic I148M variant of the gene coding for PNPLA3 has been strongly and widely correlated with a higher risk of developing severe hepatic fibrosis in patients with NAFLD/NASH and other forms of liver diseases such as alcoholic hepatitis, viral hepatitis B and C and liver cancer." (PMID 33218077, 2020). "Single nucleotide polymorphism rs738409 c.444C>G (p.Ile148Met) in the patatin-like phospholipase domain-containing protein 3 (PNPLA3) is nowadays one of the most important genetic factors with an impact on progression of several liver diseases of different etiology." (PMID 31527889, 2019). "Taken together, our PheWAS results support the hypothesis that therapeutic inhibition of PNPLA3 could treat liver diseases." (PMID 30327483, 2018). "This hypothesis is supported by the similar prevalence of portal hypertension among the different PNPLA3 genotypes." (PMID 26599080, 2015). "The presence of a PNPLA3 risk allele had no independent impact on liver disease or virological response rates to PEGIFN/RBV therapy in our cohort of HIV/HCV coinfected patients." (PMID 26599080, 2015). "In conclusion, PNPLA3 148M is over-represented in HCC patients, in particular in those with ALD&NAFLD, where it is associated with earlier presentation at a less advanced stage of liver disease." (PMID 24155878, 2013). "Our findings indicate that fibrosis progression in steatotic liver disease is mediated by an interaction of environmental risk factors (obesity, insulin resistance, alcohol consumption) and genetic risk variants, such as PNPLA3 and TM6SF2, but not by genetic variants alone." (PMID 41492318, 2026). "Moreover, modulation of PNPLA3 turnover - and its impact on long-chain polyunsaturated fatty acid remodeling - emerges as a potential therapeutic strategy for regulating lipid homeostasis in steatotic liver disease." (PMID 41802497, 2026). "Moreover, the coexistence of both the PNPLA3 G allele and SERPINA1 Pi*Z variant further amplified the risk of ACLD and CSPH, highlighting a synergistic effect of these genetic variants in the progression of liver disease and portal hypertension." (PMID 39997697, 2025). "Our findings indicate that therapies targeting ferroptosis in patients carrying the PNPLA3-I148M variant could affect the development of MASLD and ESLD and highlight the utility of iPSC-based models for the study of genetic contributions to hepatic disorders." (PMID 41118258, 2025).
liver disease (continued). "Genetic variants in PNPLA3 and HSD17B13 may be one of the targets to be knocked down by RNA interference and antisense oligonucleotide therapies, leading to the prevention of the development to severe liver diseases in patients with MASLD/MASH." (PMID 40507973, 2025). "Genetic variations in PNPLA3 were first implicated in liver diseases, including NAFLD and ALD, more than a decade ago36,37, and recently large GWASs, including a study that included our NIAAA cohort, have identified variations in PNPLA3 as having the largest effect in AC12." (PMID 38693144, 2024). "Two novel PRSs for metabolic dysfunction-associated steatotic liver disease and a PRS for cirrhosis were associated with higher risk of CLD but provided marginal predictive utility on top of other risk factors and compared to the PNPLA3 rs738409 genetic variant." (PMID 39049959, 2024). "Host genetic factors that increase the prevalence of NAFLD in the general population, such as polymorphisms in the genes encoding patatin-like-phospholipase domain-containing 3 (PNPLA3) and transmembrane 6 superfamily member 2 (TM6SF2), may also impact liver disease in PLWH." (PMID 35746590, 2022). "In addition, among patients with a SAMM50 wildtype, the presence of a PNPLA3 148M risk variant doubled in patients with alcoholic HCC compared to controls without liver disease." (PMID 36499681, 2022). "However, this pilot study was designed to be hypothesis-generating in support of a larger longitudinal study that might better define the role of PNPLA3 and other SNPs on the development of liver disease in PLWH." (PMID 33800964, 2021). "Therefore, genetic variants in PNPLA3/TM6SF2/MBOAT7/HSD17B13 do not impact the regression of portal hypertension and clinical outcomes in patients with pre-treatment ACLD after CHC cure." (PMID 33917196, 2021). "However, excessive adiposity is the major environmental determinant of the phenotypic expression of the I148M PNPLA3 variant, as concerning the development of liver disease, in individuals who do not exceed in alcohol consumption." (PMID 31375010, 2019). "Similar to the PNPLA3 I148M variant, the rs58542926 C > T variant in the TM6SF2 gene, encoding an E167K mutation, was shown to be associated with hepatic steatosis and also with increased risk of progressive liver disease and fibrosis, but its direct role in HCC predisposition is disputed." (PMID 31717576, 2019). "This review will explore the bidirectional relationship between metabolic syndrome and NAFLD, and will also discuss recent insights from studies of PNPLA3 and TM6SF2 genotypes that may give insight into how and why metabolic syndrome features and liver disease are linked in NAFLD." (PMID 26978356, 2016). "Moreover, HIV/HCV coinfected patients with a PNPLA3 risk allele are not at increased risk for development of portal hypertension and show similar SVR rates to PEGIFN/RBV therapy." (PMID 26599080, 2015). "The association between the PNPLA3 SNP and sexual dimorphism emerged over ten years ago in a meta-analysis with the aim to assess the strength of the effect of the PNPLA3 rs738409 SNP on MASLD and the severity of liver disease across different populations." (PMID 39940335, 2025). "Thus, combining assays of the PNPLA3 and SIRT5 GG genotypes as genetic risk factors may have clinical applications, as they could permit the discrimination of patients with a high likelihood of developing severe liver disease." (PMID 39596570, 2024). "An increased frequency of the heterozygous and homozygous genotype of the PNPLA3 rs738409 minor allele was observed not only in patients with alcoholic HCC but was also statistically significant in patients with alcohol-associated cirrhosis versus both control groups without liver disease." (PMID 36499681, 2022). "The late features of the liver disease in our cohort appeared to be associated only with the SERPINA1 genotype, while no significant impact of the PNPLA3 genotype was observed." (PMID 41004464, 2025).
liver disease (continued). "Interleukin 32 (IL32) mRNA expression was increased in steatotic liver disease and MASH samples solely in PNPLA3 I148M (rs738409 CG/GG) variant carriers, not in non-carriers (CC)." (PMID 40507973, 2025). "PNPLA3 is an established genetic marker of progressive liver disease, but PNPLA3 mRNA expression did not correlate to CYP2C19 activity in this cohort (r = 0.07, p = 0.68)." (PMID 37361233, 2023). "The same held true for PNPLA3 rs738409 with MAFs of 26.8% and 25.6%, respectively, in healthy controls and alcohol abusers without significant liver disease and 22.6% reported from the 1000 genome project." (PMID 36499681, 2022). "Another study found that bearing the PNPLA3 rs738409 C > G polymorphism was a risk factor for NAFLD-associated HCC, regardless of the background liver disease." (PMID 34682759, 2021). "In line, changes in non-invasive surrogates of portal hypertension (LSM/VWF/VITRO) were comparable between carriers and non-carriers of the PNPLA3 G-allele in the overall cohort." (PMID 33917196, 2021). "Despite the growing body of knowledge about TM6SF2 and PNPLA3 polymorphisms in non-alcoholic fatty liver disease, their influence in the spectrum of HCV liver disease is not yet fully defined." (PMID 33622266, 2021). "We compared the dynamics of surrogates in portal hypertension (PLT, LSM, VWF, and VITRO score) between patients with or without the PNPLA3 rs738409 G-allele in the overall study population." (PMID 33917196, 2021). "Despite the growing investigational experience with TM6SF2 and PNPLA3 polymorphisms in NAFLD, their role in the spectrum of liver disease by the hepatitis C virus is not yet fully defined." (PMID 33622266, 2021). "In conclusion, genetic variants in PNPLA3, TM6SF2, MBOAT7, and HSD17B13 do not seem to impact the short-term regression of portal hypertension." (PMID 33917196, 2021). "Liver diseases connected to FASN can thus be treated (by silencing PKLR, PCSK9 or PNPLA3) without experiencing the side effects associated with direct FASN inhibition." (PMID 28827398, 2017). "In contrast, PNPLA3 genotype did not influence clinical features at presentation in the overall series of HCC patients with other liver diseases." (PMID 24155878, 2013). "There was a significant association between PNPLA3 148M homozygosity and higher HCC grade in patients with ALD&NAFLD (10/12, 83% vs. 10/22, 45%; p = 0.03), but not in those with other liver diseases (7/10, 70% vs. 40/74, 54%; p = 0.3)." (PMID 24155878, 2013). "Interestingly, genetic variants did not influence liver disease regression in our study, although we observed a trend towards a discordancy in the evolution of CAP between carriers and non-carriers of the PNPLA3 rs738409 G-allele (i.e., decreases in non-carriers vs. increases in carriers)." (PMID 33917196, 2021). "Although hepatic macrophages play a central role in the initiation and progression of various liver diseases including MASLD, there have however, to date been no studies on the role of PNPLA3 in macrophages in metabolic liver diseases." (PMID 39394864, 2025).
Cirrhosis (134 papers, 2011 to 2026). A chronic disorder of the liver in which liver tissue becomes scarred and is partially replaced by regenerative nodules and fibrotic tissue resulting in loss of liver function. "Beyond its reproducible association with MASLD, PNPLA3 I148M has been recognized as a risk factor for steatohepatitis, fibrosis/cirrhosis, and HCC." (PMID 40166930, 2025). "The PRS (high-risk variants in PNPLA3-MBOAT7-TM6SF2-GCKR) exhibited by cirrhosis patients in the highest tertile corresponded to a 2-fold higher risk of HCC (HR = 2.05; 95% CI, 1.22–3.44)." (PMID 40507973, 2025). "One French prospective study assessed PNPLA3 genotype in >500 patients with HCV or alcohol-associated cirrhosis." (PMID 39774697, 2025). "Another recent prospective US study of 1911 patients with cirrhosis found that PNPLA3-rs738409-G carriers had a higher risk of HCC, with a greater effect in those with heavy alcohol intake, obesity, or viral hepatitis." (PMID 39774697, 2025). "The frequency of the PNPLA3 G allele was significantly higher (p < 0.0001) in the entire cirrhosis group (880/1,583; 55.6%) than in controls (1418/3402; 41.6%); OR 1.48 (95% CI 1.36–1.99)." (PMID 41004464, 2025). "The GG risk genotype of PNPLA3 was more prevalent in HCC cases compared with cirrhosis (68.3% vs. 52.5%, p = 0.002)." (PMID 40995436, 2025). "Genetic variant in PNPLA3 has been associated not only with liver fat accumulation but also with susceptibility to steatohepatitis, fibrosis, cirrhosis, and hepatocellular carcinoma." (PMID 40244110, 2025). "The frequency of the PNPLA3 G allele carriers was significantly higher (p < 0.0001) in the cirrhosis group (880 of 1583; 55.6%) than in controls (1418 of 3402; 41.6%)." (PMID 41004464, 2025). "PNPLA3 polymorphism has been associated with increased hepatic fat levels, fibrosis, cirrhosis, and hepatocellular carcinoma, while its association with CVD remains to be fully understood." (PMID 40244110, 2025). "The previously reported NAFLD variants p.Thr165Ala in MTARC1 and p.Ile148Met in PNPLA3 had proportional effects on cirrhosis." (PMID 38632349, 2024). "Among them, single-nucleotide polymorphisms (SNPs) in the patatin-like phospholipase domain containing 3 (PNPLA3) gene have been documented as the primary genetic variants associated with MASLD from simple steatosis to cirrhosis and HCC." (PMID 39596570, 2024). "On top of cardiometabolic and lifestyle risk factors, only the PRS-cirrhosis improved the C-statistic (C-statistic = 0.7345) above that of the PNPLA3 rs738409 genetic variant (C-statistic = 0.7301)." (PMID 39049959, 2024). "We found that rs738408 in PNPLA3 interacted significantly with T2D (P = 7.9 × 10−6), BMI (P = 3.0 × 10−6) and weekly alcohol intake (P = 1.2 × 10−5) on the risk of cirrhosis." (PMID 38632349, 2024). "One of these, PNPLA3 p.Ile148Met, interacts with alcohol intake, obesity and diabetes on the risk of cirrhosis and hepatocellular carcinoma (HCC)." (PMID 38632349, 2024). "PNPLA3-induced steatohepatitis patients are known to be associated with developing liver fibrosis, cirrhosis, and, ultimately, HCC." (PMID 38674389, 2024). "This highlights the potential of the PNPLA3 rs738409-GG genotype and diabetes presence in stratifying cirrhosis risk in NAFLD patients." (PMID 37892594, 2023). "The predictive model for future cirrhosis development (AUC of 0.836 95% CI: 0.769–0.904) accounted for age at onset of at-risk alcohol consumption and the number of PNPLA3 and HSD17B13 variant alleles." (PMID 37626629, 2023). "Over 50% of cirrhosis patients had at least one risk variant in PNPLA3, MBOAT7 and GCKR, while 13.0% had at least one risk variant in TM6SF2." (PMID 36854015, 2023). "One patient with cirrhosis was homozygous for the risk increasing allele of PNPLA3 (I148M) while the distribution of the other genotypes for PNPLA3 was very similar between groups." (PMID 37078380, 2023).
Cirrhosis (continued). "We previously demonstrated that age at the start of at-risk alcohol use and the PNPLA3 rs738409 variant were associated with future risk of developing cirrhosis." (PMID 37626629, 2023). "In the multivariate analysis, GGT levels (OR: 1.022; 95% CI: 1.008–1.036; p = 0.0021) and the G/G genotype of the SNP rs738409 in PNPLA3 (OR: 13.2; 95% CI: 2.2–77.5; p = 0.0040) were associated with cirrhosis." (PMID 35630668, 2022). "We found that NAFLD patients with a specific variant of a gene called PNPLA3 had a higher risk of developing cirrhosis." (PMID 36166317, 2022). "Interactions with the etiology of the cirrhosis and with the variant rs738409 in PNPLA3 are also described." (PMID 36233142, 2022). "Our results support a link between the G/G genotype in PNPLA3 and risk for the development of both cirrhosis and HCC in NAFLD." (PMID 36166317, 2022). "In this large cohort study, we found that the PNPLA3 G/G genotype was associated with a more than twofold rate for the development of cirrhosis in NAFLD." (PMID 36166317, 2022). "Carriers of the minor PNPLA3 allele are also at risk of liver fibrosis, cirrhosis, and hepatocellular carcinoma (HCC)." (PMID 36555467, 2022). "In total, 502 Pakistani CHC patients [242 males, median age 40 years, 220 with significant hepatic fibrosis, including 114 with cirrhosis] were genotyped for PNPLA3 and TM6SF2 variants using TaqMan genotyping assays." (PMID 36028802, 2022). "The GG genotype of the PNPLA3 SNP rs738409 was independently associated with cirrhosis in NAFLD patients with T2D." (PMID 35630668, 2022). "The distributions of GG genotype (P= 0.047) and G allele (P= 0.002, OR: 4.395, CI 95%: 1.622 – 11.911) of PNPLA3 (I148M) were significantly higher in total cirrhosis patients than controls." (PMID 34711009, 2021). "In this study, GG genotype and G allele distributions of PNPLA3 (I148M) variant were significantly higher in total cirrhosis patients than controls (P= 0.047), (OR: 4.395, CI 95%: 1.622–11.911) respectively." (PMID 34711009, 2021). "The distribution of GG genotype and G allele of PNPLA3 (I148M) were significantly higher in total cirrhosis patients than controls (P= 0.047), (OR: 4.395, CI 95%: 1.622–11.911) respectively." (PMID 34711009, 2021). "Upon subgroup analysis, PNPLA3 was found to be an independent risk factor for HCC in patients with NASH or ALD-related cirrhosis (OR 1.67, 95% CI 1.27-2.21)." (PMID 32102237, 2020). "We examined the association of all-cause cirrhosis with six genetic variants previously reported to be associated with alcoholic or non-alcoholic cirrhosis: PNPLA3 I48M, TM6SF2 E167K, MBOAT7 rs641738, HSD17B13 rs72613567, HFE C282Y and SERPINA1 E366K." (PMID 32282858, 2020). "Known NAFLD and cirrhosis risk alleles in PNPLA3 and TM6SF2 were also associated with both elevated cT1 and MRI-derived PDFF in our cohort." (PMID 32247823, 2020). "More recently, we have reported that the rs738409 PNPLA3 SNP is associated not only generically with NAFLD fibrosis but also specifically with the evolution to NASH cirrhosis." (PMID 29732362, 2018). "The PNPLA3 I148M variant was also associated with HCC development outside cirrhosis, with a similar effect size of that of MBOAT7 variation (p = 0.021)." (PMID 28674415, 2017). "This PNPLA3 I148M variant has been associated to higher accumulation of fat in liver, steatohepatitis and inflammation, progression to fibrosis/cirrhosis and liver cancer." (PMID 29116096, 2017). "Our study, which was carried out in a larger sample, identified the presence of PNPLA3 rs738409 G allele as an independent risk factor for cirrhosis in HIV/HCV-coinfected patients." (PMID 27973562, 2016). "An association between PNPLA3 rs738409 and cirrhosis or advanced fibrosis was also reported in patients with NAFLD, alcoholic liver disease or chronic hepatitis C." (PMID 26950933, 2016).